BRCA2 (BRCA2 DNA repair associated)
Diseases named in the same sentence as BRCA2 in open-access papers (continued):
Sharing a sentence is not in itself a finding about the gene and the disease.
ovarian carcinoma (continued). "Recently, Gabai-Kapara and coworkers have performed a population-based screening for ovarian cancer risk due to BRCA1 and BRCA2 in the Ashkenazi Jewish population of Israel; it was estimated that in this population 40% of ovarian cancers are due to BRCA1 and BRCA2 mutations." (PMID 29389895, 2018). "A meta-analysis showed that BRCA2 mutation carriers did not have a significant reduction in risk of ovarian cancer while women with BRCA1 mutation did." (PMID 30174725, 2018). "In addition to the presence of either BRCA1 or BRCA2 mutations in breast and/ovarian cancer patients, there are reports of patients being double heterozygous for both BRCA1 and BRCA2 mutations." (PMID 29459887, 2018). "While the general population lifetime risk of ovarian cancer is low at 1.4%, women at high-risk of developing the disease due to their inheritance of a germline BRCA1 and BRCA2 mutation have an average cumulative risk of between 40% to 75% and 11% to 34%, respectively." (PMID 29506471, 2018). "With BRCA status providing prognostic information and helping to predict sensitivity to cytotoxic agents, ovarian cancer management now sees patients “being selected in clinical practice for biomarker-directed therapy, based on presence of a BRCA1 or BRCA2 mutation”." (PMID 29752676, 2018). "The only isolated population subgroup that might benefit from ovarian cancer screening tests is patients with mutations within the BRCA1 and BRCA2 genes and burdened by a family history of ovarian cancer." (PMID 28182133, 2017). "We found that ovarian cancer patients with BRCA2-mutation had significantly longer OS than non-carriers, regardless of research center, duration of follow-up or histologic type." (PMID 27690218, 2017). "Risk reduction strategies are most relevant to women identified as carrying a BRCA1 or BRCA2 mutation who have not yet developed cancer and the role of risk-reducing surgery in the management of hereditary breast and ovarian cancer is already well established." (PMID 28780755, 2017). "A novel LGR BRCA2/ex1-14del was found in 0.9% of Colombian breast/ovarian cancer families." (PMID 28680148, 2017). "He studied Ovarian Cancer Cluster Region (OCCR) within the BRCA2 coding sequence." (PMID 28814288, 2017). "The unweighted BRCA1- and BRCA2-specific PRS for breast and ovarian cancer, constructed on the basis of association results in CIMBA, showed strong evidence of association with breast and ovarian cancer (available online)." (PMID 28376175, 2017). "A similar likelihood of progression-free survival was shown after five years in a large cohort of women with FIGO stage III or IV epithelial ovarian cancer but these studies did not take BRCA1/BRCA2 mutation status into account." (PMID 28780755, 2017). "The present meta-analysis with the largest number of patients investigated both survival (OS) and progression outcomes (PFS) for ovarian cancer, incorporating not only the general BRCA mutation status but also two subtypes, including BRCA1 and BRCA2 mutation status." (PMID 27690218, 2017). "Similar to BRCA1, BRCA2 dysfunction is commonly found in breast and ovarian cancer." (PMID 28471392, 2017). "These associations provide strong support for the hypothesis of a polygenic component for breast and ovarian cancer risks, respectively, that is largely shared between the general population and BRCA1 and BRCA2 mutation carriers." (PMID 28376175, 2017). "The highest discrimination was achieved by the ovarian cancer PRS in BRCA2 carriers." (PMID 28376175, 2017).
ovarian carcinoma (continued). "For women with ovarian cancer and a BRCA1/BRCA2 germline mutation who are interested in risk-reducing breast surgery, realistic information should be presented in an individualized way, in order to facilitate women making decisions about their own life and body." (PMID 28780755, 2017). "If and when risk-reducing breast surgery in BRCA1/BRCA2 carriers with a previous diagnosis of ovarian cancer is appropriate is not easily answered by current research evidence." (PMID 28780755, 2017). "Here, we show that this combined approach allows the rapid and reliable detection of both germline and somatic aberrations affecting BRCA1 and BRCA2 in DNA derived from FFPE OCs, enabling improved hereditary cancer risk assessment and clinical treatment of ovarian cancer patients." (PMID 27767231, 2017). "In the 179 probands analyzed, an expectable correlation was found between cancer type and gene mutation: we found most cases with ovary cancer diagnosis to have mutations in BRCA1, 12 cases (one novel) compared with probands with a mutation in BRCA2, 2 cases (one novel)." (PMID 28947987, 2017). "The results may also help to deepen our understanding of the biology of ovarian cancer development in BRCA1 and BRCA2 mutation carriers, potentially leading to the development of more effective and personalized treatments." (PMID 27463617, 2016). "In our previous study, of a group of 34 women with ovarian cancer and a family history of GC and 75 women with ovarian cancer and a family history of ovarian cancer but not stomach cancer were compared according to the presence of BRCA2 mutations." (PMID 26779294, 2016). "Hence, the purpose of our work was to screen the entire BRCA1 and BRCA2 genes in a series of patients with epithelial ovarian cancer unselected for age or family history for breast and/or ovarian cancer treated in Brazil." (PMID 27914478, 2016). "More than a half of the tested breast/ovarian cancer patients originating from FVG and neighboring geographic areas of Veneto (Italy) and Istria (Slovenia and Croatia) were found to be carrier of one of the 8 BRCA1 or BRCA2 recurrent mutations." (PMID 26852130, 2016). "Conservative methods of prevention also failed to reduce the mortality due to ovarian cancer in a group of high-risk patients – carriers of the BRCA1 or BRCA2 gene mutations." (PMID 26928677, 2016). "In addition, although loss of heterozygosity was discovered in 41 ovarian cancer cell lines generally used in most laboratories, it was rare to find a complete loss of function caused by both of BRCA1 and BRCA2 mutations." (PMID 27385216, 2016). "This work provides a rationale for combining BRCA2 ASO and olaparib treatment and extends the applicability of olaparib clinically, which up until now has been used primarily in the context of BRCA1 or 2 mutated ovarian cancers." (PMID 26959114, 2016). "The same author analyzed 1171 unmatched ovarian cancer cases and investigated the presence of selected BRCA1 and BRCA2 mutations and, on the basis of his data, showed that the relative risk of developing stomach cancer in BRCA1 mutation carriers was 4.8 (95 % CI 1.5–15)." (PMID 26779294, 2016). "The 4q32.3 locus is associated with ovarian cancer risk in BRCA1 but not in BRCA2 mutation carriers or the general population, while the opposite is true for the locus 17q11.2." (PMID 27463617, 2016). "HBOC patients do not carry a BRCA1 or BRCA2 mutation but have an increased risk of developing breast and ovarian cancer." (PMID 26768420, 2016). "Although the estimated cumulative incidence of ovarian cancer by the age of 70 is 40% (95% CI 35–46%) for BRCA1 and 18% (95% CI 13–23%) for BRCA2 mutation carriers, the precise risk estimates vary according to the population under study, ascertainment method and applied statistical technique." (PMID 27914478, 2016).
ovarian carcinoma (continued). "It was suggested that because EMSY amplification could mimic a BRCA2 mutated state, it could account for BRCAness in sporadic breast and ovarian cancers with intact BRCA2 and possibly predict hypersensitivity to PARP inhibitors." (PMID 27642590, 2016). "Indeed, germline and somatic mutations in HR genes occur in about 30% of patients with ovarian carcinoma, of which up to 75% are in BRCA1 and BRCA2 genes." (PMID 26745875, 2016). "In this regard, it is relevant that mammalian cells lacking the major hereditary breast/ovarian cancer predisposition genes BRCA1 or BRCA2 or other cancer predisposition HR genes reveal a bias towards LTGC." (PMID 27832076, 2016). "We tested whether BRCA2 downregulation could sensitize two different ovarian cancer cell lines to olaparib treatment." (PMID 26959114, 2016). "However, only 7–9% of sporadic ovarian cancers exhibit BRCA1 30 mutations leading to inactivation of BRCA1, while 4% exhibit BRCA2 mutations." (PMID 26800494, 2016). "BRCA1 and BRCA2 germline variant screening using Sanger DNA sequencing or NGS is well established in clinical practice and is used primarily for the determination of hereditary breast and ovarian cancer risk." (PMID 25859162, 2015). "Analysis of the expanded 34 burden test genes revealed that patients with germline BRCA1 and BRCA2 truncations had significantly higher somatic mutation frequencies than cases without such changes in both breast and ovarian cancers." (PMID 26689913, 2015). "BRCA2 and BRCA1 germline mutations were identified in patients 4453 and 4485, respectively, as a consequence of genetic testing in hereditary cancer clinics due to their breast and ovarian cancer family history (see Figure supplemental S1 for pedigree)." (PMID 26622941, 2015). "Interest is alsoincreasing in expanding testing for somatic mutations in ovarian cancer,particularly for genes such as BRCA1 and BRCA2, wherebymutations may allow more patients to benefit from targeted agents, includingpoly(ADP-ribose) polymerase inhibitors." (PMID 26669451, 2015). "Other »high risk« ovarian cancer genes may exist, although mutations in these genes are probably less common than BRCA1 and BRCA2." (PMID 25810703, 2015). "The rationale was based on the evidence that 50% of patients who carry BRCA1 and BRCA2 mutations have no close family history of breast or ovarian cancer." (PMID 25729421, 2015). "In order to assess the feasibility of offering genetic testing of women with ovarian cancer, it is important to determine the frequency of BRCA1 and BRCA2 mutation carriers in populations where genetic testing is available as the prevalence may vary." (PMID 25884701, 2015). "The tumor suppressors BRCA1 and BRCA2 play a central role in the maintenance of chromosomal stability and germline mutations in BRCA1 and BRCA2 genes have been detected in approximately 90% of hereditary breast/ovarian cancers." (PMID 26779440, 2015). "While the general population lifetime risk of ovarian cancer is 1.4 %, women at high-risk of developing the disease due to their inheritance of a germline BRCA1 and BRCA2 mutation have an average cumulative risk of between 40 % to 75 % and 8 % to 34 %, respectively." (PMID 27231565, 2015). "In addition to germline mutations, at least another 2–8 % of ovarian cancers have somatic BRCA1 and BRCA2 mutations, so that up to 20 % of patients with ovarian cancer have a BRCA1 or BRCA2 deficiency triggered by a mutation." (PMID 26109557, 2015).
ovarian carcinoma (continued). "For model development, genetic data will involve genetic testing of high penetrance genes associated with hereditary breast and ovarian cancer, BRCA1 and BRCA2, as well as lower penetrance genes associated with ovarian cancer susceptibility, BRIP1, RAD51C and RAD51D." (PMID 25391615, 2015). "In conclusion, our results indicate that although K3326* does not have the same clinical significance as other BRCA2 truncating mutations located more 5′ in the gene, its impact on modifying breast and/or ovarian cancer is not negligible." (PMID 26455428, 2015). "Sixteen different FA genes have now been identified whose products act in a common pathway of DNA interstrand crosslink repair, and some of them (including BRCA2/FANCD1, BRIP1/FANCJ, PALB2/FANCN, and RAD51C/FANCO) have also been described as breast and ovarian cancer susceptibility genes." (PMID 24465539, 2014). "Moreover, the role of PARP inhibitors for chemoprevention for breast and ovarian cancer in BRCA1 and BRCA2 mutation carriers has been proposed." (PMID 24317580, 2014). "However, it must still be interpreted with caution due to small number of ovarian cancer cases in the BRCA2 group." (PMID 24698998, 2014). "In another study 11.5% of all ovarian cancer cases in Colombia were attributable to a single BRCA1 founder mutation, while 15.6% of the total cohort was positive for mutations in either BRCA1 or BRCA2." (PMID 23536787, 2013). "BRCA1/BRCA2 mutation-negative Spanish high risk breast/ovarian cancer families with pancreatic cancer cases." (PMID 23935836, 2013). "It has also been noted that not all mutations in BRCA1 and BRCA2 are highly penetrant for breast or ovarian cancer." (PMID 24025454, 2013). "Notably, these families had a similar phenotype to BRCA2, with an increased incidence of pancreatic as well as breast and ovarian cancers." (PMID 23586058, 2013). "Apart from breast and ovarian cancer, BRCA1 and BRCA2 carriers might be at higher risk for additional malignancies such as prostate, colorectal, familial melanoma and pancreatic cancers." (PMID 23935836, 2013). "Most BRCA gene studies in ovarian cancer have centered around the differential chemosensitivity profile known as “BRCAness syndrome” in selected patients with inherited BRCA1 and BRCA2 mutations who are reported to show enhanced sensitivity to platinum-based anticancer drugs." (PMID 23289505, 2013). "BRCA2, like BRCA1 is a gene that has been causally linked to both breast and ovarian cancer." (PMID 24244370, 2013). "In 2003, Cass and colleagues made the surprising observation that a group of ovarian carcinoma patients with BRCA1 and BRCA2 mutations had a significantly higher (72%) response rate to primary platinum-based chemotherapy than patients with sporadic disease (36%)." (PMID 23344037, 2013). "Of these, the 4q32.2 locus was associated with ovarian cancer risk for BRCA1 carriers but not for BRCA2 carriers or in the general population." (PMID 23544013, 2013). "A number of women without a family history of early onset breast or ovarian cancer discovered that they carry a BRCA1 or BRCA2 mutation that conveys a high risk." (PMID 23638402, 2013). "However, clinicopathologic studies have shown most ovarian cancers with germline BRCA1 and BRCA2 mutations to be morphologically and clinically similar to sporadic ovarian cancer." (PMID 23289505, 2013). "Notable in this pedigree is that lack of ovarian cancer cases typified by BRCA1 or BRCA2 mutation carrier families." (PMID 23302520, 2013).
ovarian carcinoma (continued). "Recent histopathological studies on early stage lesions of ovarian cancer in BRCA1 or BRCA2 carriers have suggested that the primary origin of high-grade serous ovarian cancer is the fallopian tube, implicating both genes as key players in the fallopian differentiation." (PMID 23536787, 2013). "Biallelic or in the case of FA-B hemizygous mutations in any one of the underlying genes lead to FA, while monoallelic mutations in FANCD1 (BRCA2), FANCJ (BRIP1), FANCN (PALB2) or FANCO (RAD51C) increase the risk of carriers for developing breast and ovarian cancer." (PMID 23285130, 2012). "In fact, when variants with particularly large effects do exist—such as APOE in Alzheimer’s disease, BRCA1 and BRCA2 in breast and ovarian cancer, and LRRK2 in Parkinson’s disease —previous authors have suggested simulations in lieu of their analytical approximation." (PMID 22827772, 2012). "The lifetime risks of ovarian cancer are 54% for BRCA1 and 23% for BRCA2 mutation carriers." (PMID 22330607, 2012). "Our analysis of rare CNVs in a small cohort of BRCA1/BRCA2 mutation-negative breast and/or ovarian cancer families suggests an intriguing excess in the proportion of rare CNVs compared to controls." (PMID 22314128, 2012). "The cell lines did not harbor the most commonly reported KRAS or BRAF mutations nor the most common BRCA1 and BRCA2 mutations identified in the French Canadian breast and ovarian cancer families." (PMID 22931248, 2012). "RAD51D should be included in genetic screening of ovarian cancer families that do not have BRCA1/BRCA2 mutations." (PMID 22415235, 2012). "Interestingly, only 5–10% of women with ovarian cancer have inherited genetic mutations in tumor suppressor genes such as BRCA1 and BRCA2 that predisposes them to breast and ovarian cancer." (PMID 22685544, 2012). "Increased sensitivity of BRCA2-deficient ovarian cancer cell line TOV81 to cisplatin, but not to camptothecin or paclitaxel, as assessed by a cell survival assay." (PMID 21819606, 2011). "Inherited mutations in the breast cancer susceptibility gene 1 (BRCA1) [MIM 113705] and breast cancer susceptibility gene 2 (BRCA2) [MIM 600185] are associated with a high risk of developing breast and ovarian cancers in females of different age and ethnic groups." (PMID 21559243, 2011). "This marked reduction in cost will enable BRCA1 and BRCA2 mutation detection to be more widely used especially for those who have a positive family history for breast or ovarian cancer but who do not meet current algorithms for mutation testing." (PMID 21702907, 2011). "Several likely pathogenic RAD51C mutations have been identified in BRCA1- and BRCA2-negative breast and ovarian cancer families." (PMID 21980511, 2011). "At this time, the NCCN and ACOG guidelines suggest that for patients with BRCA1 or BRCA2 mutations, pelvic ultrasound and CA125 every 6 months may be considered for the detection of early ovarian cancer." (PMID 22312502, 2011). "The aim of these consortia’s is to combine data from many studies, to provide a reliable assessment of the breast and ovarian cancer risks associated with different genetic and environmental factors, and to identify potential modifiers of cancer risk in carriers of BRCA1 and BRCA2 mutation." (PMID 21639959, 2011). "Breast and ovarian cancer cells lacking function of either the BRCA1 or BRCA2 susceptibility gene products are deficient in homologous recombination and more sensitive to platinum-containing drugs." (PMID 21679440, 2011). "To further investigate the role of RAD51C as an HBOC predisposition gene, we performed complete sequencing of RAD51C to screen for mutations in 286 BRCA1- and BRCA2-negative breast and/or ovarian cancer cases with a family history of breast and ovarian cancer." (PMID 21980511, 2011).